VDR (vitamin D receptor)
Diseases named in the same sentence as VDR in open-access papers (continued):
Sharing a sentence is not in itself a finding about the gene and the disease.
Obesity (continued). "This was done to explore the mechanisms underlying the suggested role of the VD/VDR complex in the pathogenesis of obesity." (PMID 37848505, 2023). "Polymorphisms in the vitamin D receptor (VDR) gene have been linked to adiposity phenotypes and obesity." (PMID 37432159, 2023). "Several genetic loci are associated with obesity and melanoma risk, including Agouti signaling protein, interferon regulatory factor 4, peroxisome proliferator-activated receptor-coactivator 1 and vitamin D receptor." (PMID 37777736, 2023). "Studies of the relationships between VDR gene polymorphisms and obesity-related diseases need to be powerful enough to detect a statistically significant association if one exists." (PMID 37189820, 2023). "This indicates that the degree of obesity is associated with the response of adipose tissue to VD via VDR and VDR is involved in the alternations in adipose tissue during the progression of obesity." (PMID 36771240, 2023). "Altogether, these data show that obesity is linked to deficient VDR signalling, which is further associated with increased IRF7 expression." (PMID 36443525, 2022). "Some studies have found relationships between VDR polymorphisms and BMI, adiposity markers, or obesity and other research has found a relationship between BMI and polymorphisms of VDBP and CYP27b1." (PMID 35631190, 2022). "A recent study examined the relationship of VDR polymorphisms and weight loss in a weight-loss program (not KD) with supplementation of vitamin D; while in another, polymorphisms in VDR were related to obesity." (PMID 36557329, 2022). "Paediatric obesity was associated with compromised expression of VDR-controlled gene networks in the adipose tissue of children and lower expression of CYP27A1, which is involved in the initial activation of Vit-D3." (PMID 36443525, 2022). "Association of VDR polymorphism with diseases like tuberculosis, osteoporosis and obesity has been reported earlier." (PMID 34824904, 2021). "The current study therefore aimed to determine the possible association between VDR polymorphisms and diabetic phenotype, and obesity, among Malaysian patients with T2DM." (PMID 33567588, 2021). "Our findings suggested an association between the VDR ApaI polymorphism (rs7975232 C/A) and the susceptibility to obesity while the A allele and the AA genotype in ApaI were associated with obesity phenotypes." (PMID 34936251, 2021). "In the current study, a significant association between TaqI VDR SNPs and obesity phenotype was found when studied groups were subdivided according to the presence of osteoporosis." (PMID 34351532, 2021). "The relationships of the VDR gene polymorphisms with the anthropometric and biochemical features of obesity were evident in the higher serum levels of FBS and BMI in genotype AA carriers." (PMID 34936251, 2021). "rs7975232 polymorphism of VDR gene was found to be positively correlated with obesity according to skin fold thickness and body fat rate in Chinese Han population." (PMID 34745225, 2021). "Risk factors are different in many populations and several VDR gene variants appear to affect obesity differently." (PMID 34936251, 2021). "Even though the association between VDR SNPs and metabolic diseases remain inconsistent, some positive associations showing potential effects on obesity and T2D in specific ethnic groups were identified." (PMID 33553043, 2020). "Twelve Studies have investigated the association between the VDR ApaI polymorphism and obesity traits and four of them have reported significant associations in the Chinese, Vietnamese and Czech populations (n = 140–882)." (PMID 33553043, 2020). "The vast majority of the associations (56 associations) were identified in the vitamin D metabolism-related genes (CYP24A1, GC and VDR) and, in particular, the VDR gene SNPs showed 48 significant associations with obesity outcomes." (PMID 33553043, 2020).
Obesity (continued). "Thirteen studies have examined the association between the VDR BsmI SNP and obesity-related traits, of which nine have reported a significant association in the Arab, Brazilian, Polish, French, Swedish, and Vietnamese populations (n = 140–891)." (PMID 33553043, 2020). "Fourteen studies have examined the association between the VDR TaqI polymorphism and obesity traits, of which six have shown significant association in several populations including Saudi, Czech, Greek, French, and Chinese (n = 184–891)." (PMID 33553043, 2020). "Intestinal VDR deficiency extensively alters primary and secondary bile acid metabolites and bile acids are known to shape the gut microbiome especially in obesity." (PMID 32355205, 2020). "In the current study, we have demonstrated that targeted deletion of VDR in intestinal or myeloid cells distinctively transformed metabolite profiles and the gut microbiome, leading to an increased risk of obesity." (PMID 32355205, 2020). "A study in American Caucasian women (n = 1,773) showed a significant association of five VDR SNPs (rs739837, rs2239179, rs3819545, rs3782905, and rs4760648) with obesity outcomes." (PMID 33553043, 2020). "Evidence shows that low serum vitamin D concentrations account for an increased risk of obesity by inducing vitamin D receptor (VDR) hypofunction." (PMID 30975133, 2019). "We found that obesity was associated with increased VDR mRNA levels in adipose tissues, while in the case of CYP27B1, an opposite trend was observed." (PMID 31652924, 2019). "The most common VDR polymorphisms reported to be associated with cancer and obesity are BsmI (rs1544410), ApaI(rs7975232), TaqI (rs731236), FokI (rs2228570) and Cdx2 (rs 11,568,820)." (PMID 31395070, 2019). "A number of biological processes and diseases, such as Alzheimer's disease, autism, type 2 diabetes mellitus, obesity, and rheumatoid arthritis, associate with VDR polymorphisms." (PMID 31534963, 2019). "Due to the presence of an abundance of vitamin D receptors (VDR) on adipocytes, the association between vitamin D and obesity has been the focus of attention." (PMID 29321608, 2018). "The Vitamin D/VDR axis plays a crucial role in obesity, which is at least partially mediated by gene polymorphisms and inflammation." (PMID 30828578, 2018). "On the contrary, a study in transgenic mice showed that over-expression of human VDR in adipocytes caused decreased energy expenditure and induced obesity." (PMID 29343214, 2018). "Apart from obesity and metabolic syndrome, decreased vitamin D and downregulation of VDR are also linked with the pathogenesis of several diseases associated with microbial dysbiosis, namely IBD." (PMID 30828578, 2018). "The aim of this study was to investigate the association of candidate gene single nucleotide polymorphisms (SNPs), namely FTO (rs9939609) and VDR (rs1544410), with obesity in the UAE population." (PMID 29343214, 2018). "Induction of white adipocyte trans-differentiation into metabolically active beige adipocytes is an attractive target in anti-obesity therapeutics, and loss of VDR signaling appears to be a contributing factor." (PMID 30828578, 2018). "The rs1544410 VDR SNP is one of the most well studied VDR SNPs in the Arab population with mixed results reported for its association with obesity traits especially within the Gulf Cooperation Council countries." (PMID 29343214, 2018). "Genetic variants in VDR gene have been reported to be associated with MS and its components including anthropometric parameters related to obesity, insulin resistance, T2DM, and atherogenic lipid abnormalities in different populations." (PMID 30166978, 2018). "Association between VDR BsmI and risk of obesity in Malaysian adolescents presented as OR (unadjusted and adjusted) with 95% CI." (PMID 28617856, 2017).
Obesity (continued). "Risk of obesity and insulin resistance with A allele of VDR BsmI polymorphism compared to G allele in Malaysian adolescents when stratified according to Vitamin D status presented as adjusted OR with 95% CI." (PMID 28617856, 2017). "It is empirically known that obesity is associated with vitamin D status but the underlying pathophysiology has been uncertain and the role of vitamin D receptor variability in obesity is far from being understood." (PMID 28830368, 2017). "The rs1544410 or BsmI single nucleotide polymorphism (SNP) in the intronic region of the VDR gene has been previously associated with vitamin D levels, obesity and insulin resistance." (PMID 28617856, 2017). "The BsmI polymorphism in the VDR gene has been described as a possible genetic marker for different clinical conditions such as type 1 diabetes, obesity and some types of cancers." (PMID 27066374, 2016). "As contradictory as it seems, VDR or CYP27B1 knocked-out mice show great fat mass loss while obesity in humans is commonly associated with poor vitamin D plasmatic levels." (PMID 27579030, 2016). "Results of these analyses showed that VDR polymorphisms located in 3′ haplotype block region of VDR gene correlate with obesity development." (PMID 25020064, 2014). "Haplotype association with obesity was evaluated by verifying the distribution of VDR haplotypes in obese vs. lean subjects." (PMID 25020064, 2014). "Individual characteristics influence the response to the vitamin, such as the presence of obesity, which can increase the vitamin D demand, and the type of polymorphism of the vitamin D receptor." (PMID 24747593, 2014). "Analysis of possible associations between VDR polymorphisms and obesity showed the presence of a strong association of the rs731236 (G) and rs1544410 (T) VDR minor alleles with higher BMI values independently of age and sex." (PMID 25020064, 2014). "We investigated possible associations of the three known VDR SNPs rs731236(A/G)(TaqI), rs1544410(C/T)(BsmI) and rs7975232 (A/C)(ApaI) with obesity in a population from Saudi Arabia, a country where obesity is reaching endemic proportions." (PMID 25020064, 2014). "Variables (including age and VDR minor alleles) with a positive β value are associated with higher BMI, therefore to a higher risk of obesity after adjustment for all the other covariates." (PMID 25020064, 2014). "Data herein indicate that polymorphisms affecting the vitamin D/VDR axis play a role in obesity that is associated with an ongoing degree of inflammation, possibly resulting from alterations of gut permeability and microbial translocation." (PMID 25020064, 2014). "The VDR TaqI allele is associated with obesity; BsmI and ApaI VDR genes are also significantly associated with overweight and obesity, and the BsmI VDR polymorphism appeared to influence body mass index." (PMID 23800102, 2013). "Other factors such as mutations in vitamin D receptor (VDR) polymorphism, low daily calcium intake, obesity and low social status have all been associated with low circulating vitamin D levels." (PMID 22759399, 2012). "The weaker association observed in obesity could reflect impaired vitamin D receptor signaling or chronic immune desensitization." (PMID 41614735, 2025). "Moreover, a polymorphism of Apal (rs7975232 C > A) in the VDR gene increases the risk of developing obesity in the Bangladeshi population." (PMID 41264635, 2025). "Despite the limitations, ours is the first case-control study that we are aware of that has identified the association between VDR gene polymorphisms, ApaI (rs7975232), with obesity in the Bangladeshi population, along with lower serum 25-hydroxy vitamin D level and lower serum VDR levels." (PMID 41264635, 2025). "Genetic studies suggest that VDR polymorphisms may influence fat distribution and obesity risk, although the evidence remains inconclusive, and Mendelian randomization analyses suggest that obesity itself is the primary driver of reduced 25(OH)D levels." (PMID 41226298, 2025).
Obesity (continued). "Moreover, we examined the association of the VDR gene polymorphisms ApaI (rs7975232) and TaqI (rs731236) with obesity." (PMID 41264635, 2025). "In particular, the polymorphism named ApaI (rs7975232) and TaqI (rs731236) of the VDR gene have been extensively studied and shown a positive association with obesity in Saudi, Iranian, Korean, Greek, and Chinese populations whereas negative associations have also been reported." (PMID 41264635, 2025). "Genetic variants of the VDR are also significant for weight gain and the development of obesity, and may also affect both the activity of the receptor itself and serum vitamin D levels." (PMID 39458556, 2024). "The mechanism by which vitamin D might mediate the association between obesity and inflammation might involve its hormonal form of vitamin D, calcitriol, which has immunomodulatory properties through the vitamin D receptor (VDR)." (PMID 39408928, 2024). "Moreover, the VDR expression decreases with the adipocytes’ differentiation progress, which influences the obesity-related risk." (PMID 39458556, 2024). "The VDR alleles (G) rs731236 (TaqI) and (T) rs1544410 (BsmI) might increase the risk of obesity, as they were associated with higher body mass index values in obese individuals." (PMID 37175993, 2023). "The report suggested that both bb of BsmI and tt of TaqI genotypes were higher in the obese group compared with the lean group and that low vitamin D levels and VDR BsmI and Taq1 genotypes may be a risk factor of obesity." (PMID 37189820, 2023). "There is still, however, the need for large well-designed epidemiological studies to evaluate the relationships between VDR gene polymorphisms and obesity-related diseases in an appropriate representative sample of the target population to which the findings will be referred." (PMID 37189820, 2023). "Also, the results of the present study indicate that VDR and ADRs genetic polymorphisms seem to influence vitamin D supplementation response and obesity markers." (PMID 35308505, 2022). "The association between FokI VDR polymorphisms and obesity has been uncovered in a previous study." (PMID 35282461, 2022). "Another example of the converse relationship between vitamin D concentration and VDR levels has been reported in patients with insulin resistance and obesity, who have been found to have deficient levels of vitamin D on the one hand but increased levels of VDR in adipose tissue on the other." (PMID 35822270, 2022). "This study proposes that the FokI VDR polymorphism could have an impact upon key components of MetS, including obesity, dyslipidemia, and GDM." (PMID 35282461, 2022). "Another hypothesis that supports the involvement of vitamin D deficiency in the pathophysiology of obesity is that 1,25(OH)2D and VDR are implicated in adipocyte differentiation." (PMID 35308505, 2022). "We found relationships between the VDR gene ApaI polymorphism and obesity in an Iranian population." (PMID 34936251, 2021). "Another example of the converse relationship between vitamin D concentration and VDR levels has been reported in patients with insulin resistance and obesity, who have been found have deficient levels of vitamin D on the one hand but increased levels of VDR in adipose tissue on the other." (PMID 34725922, 2021). "Variations in VDR genetic alleles have been demonstrated to be associated with metabolic syndrome (MS) and its components including anthropometric parameters related to obesity." (PMID 34351532, 2021). "A significant association was found between heterozygous CT genotype of FokI (VDR 2228570 C > T) and risk of obesity among healthy controls (p = 0.035), such that healthy participants with a heterozygous CT genotype had a 92% lower likelihood of becoming obese." (PMID 33567588, 2021). "We found that VDR ApaI (rs7975232 C/A) polymorphism appeared to be a risk factor for obesity." (PMID 34936251, 2021).
Obesity (continued). "Three Studies have investigated the association between the VDR Cdx2 SNP and obesity traits." (PMID 33553043, 2020). "Twelve Studies have investigated the association between the VDR FokI polymorphism and obesity traits and only three of these have been consistent in reporting a significant association in Caucasian men (n = 302) and Czech (n = 517) and Chinese (n = 882) populations." (PMID 33553043, 2020). "As BMI and WC cannot distinguish fat from lean mass, explicit understanding of these two obesity biomarkers may provide important insights into the association between VDR variants and BMI or WC in different studies." (PMID 30975133, 2019). "Although our findings were limited to visceral fat depots, based on them, we hypothesize that miRNAs may play a decisive role in the obesity-associated changes in VDR expression." (PMID 31652924, 2019). "Primarily 4 VDR polymorphisms, including the rs10735810 FoKI SNP and 3 additional ones (the rs7975232 ApaI, the rs1544410 BsmI, and the rs731236 TaqI), have been analyzed in relation to genetic predisposition to obesity; however, findings are contradictory." (PMID 30881343, 2019). "Thus, the overall effect of low vitamin D/VDR activation is increased susceptibility to obesity and associated diseases." (PMID 30828578, 2018). "Our study suggests that genetic variability in the VDR region may be an important factor influencing anthropometric characteristics associated with obesity." (PMID 28830368, 2017). "Obesity affects vitamin D metabolism and reduces serum 1,25 (OH)2D3 level, which involves the sequestration and volume dilution of cholecalciferol by fat, changes in vitamin D metabolic enzymes in adipocytes, and the influence of genetic factors such as VDR mutation." (PMID 40630116, 2025). "However, case–control and family-based studies in China demonstrated that VDR rs3847987 may be associated with obesity and hypertension." (PMID 38397449, 2024). "Also, other variables could influence the results of interventional studies, such as physical activity, obesity, VDR polymorphisms, or the heterogeneity of populations." (PMID 38674837, 2024). "Furthermore, the influence of underlying vitamin D receptor (VDR) genetic polymorphisms which have been linked to diseases such as obesity remains unclear." (PMID 39452905, 2024). "Additionally, VDR has been proposed as a potential key player in the pathogenesis of obesity, through the discovery of a strong association between the VDR TaqI ‘T’ allele and obesity in a Greek population." (PMID 39328465, 2024). "Also, there is association between gene polymorphism of VDR and obesity." (PMID 37025056, 2023). "In addition, the absence of the BB genotype is also associated with increased body weight and fat mass, suggesting that variations in VDR polymorphisms in women may predispose them to both poorer lower limb strength and obesity." (PMID 30759736, 2019). "Ruiz-Ojeda in the 1,020 review draws the following conclusions: obesity reported that associations with VDR polymorphisms could be related to either a direct effect of vitamin D in adipocyte differentiation and metabolism, or an indirect effect by modulation of insulin secretion." (PMID 30881343, 2019). "In conclusion, data from this study confirm that the genetic variability in the VDR region may be an important factor influencing anthropometric parameters associated with obesity, i.e. waist circumference, sum of skin fold thickness and total % of body fat in the Central-European population." (PMID 28830368, 2017). "Furthermore, certain vitamin D receptor (VDR) polymorphisms are associated with obesity." (PMID 25255691, 2014). "Furthermore, VDR haplotypes that are associated with statistically increased or reduced risks of obesity and with higher/lower BMI scores could be identified." (PMID 25020064, 2014).